IL24 (interleukin 24)
Diseases named in the same sentence as IL24 in open-access papers (continued):
Sharing a sentence is not in itself a finding about the gene and the disease.
prostate carcinoma (continued). "Combination of Ad-IL24 and human tumor necrosis factor-alpha (rhTNF) also showed synergistic therapeutic effect in human prostate cancer cells." (PMID 24377906, 2013). "In contrast, overexpression of Bcl-2 protected prostate cancer cells from MDA-7/IL-24-mediated apoptosis, suggesting Bcl-2 plays an important role in cancer cell apoptosis in response to MDA-7/IL-24." (PMID 22629368, 2012). "The present study has shown that the MDA-7/IL-24 cytokine also inhibits the adhesion, motility and growth of prostate cancer cells." (PMID 21524313, 2011). "Considering the well-documented role of GSK3β in cancer progression and resistance to therapy, our findings indicate that IL-24-based treatments might provide a novel approach to targeting prostate cancer cells while reducing effects on normal tissues." (PMID 40072085, 2025). "H-89 inhibited IL-24-mediated killing in human prostate cancer cell lines." (PMID 40072085, 2025). "IL-24 activates PKA in all human prostate cancer cell lines." (PMID 40072085, 2025). "Additionally, synergistic anti‐tumor effects have been observed upon using ZD55‐IL‐24, an oncolytic adenovirus containing IL‐24, in combination with radiation in prostate cancer models." (PMID 40338095, 2025). "Similarly, the DNM2-dependent endocytosis of the Interleukin 24 (IL-24) with its receptor is required in prostate cancer cells for the tumor suppressor action of the IL-24 (also called MDA-7)." (PMID 34294140, 2021). "Additionally, the combination of secreted MDA-7/IL-24 and radiation induced a potent “bystander” antitumor effect in both sensitive and resistant prostate cancer cells." (PMID 35008495, 2021). "Additionally, miR-205 positively regulates transcriptional activation of the tumour-suppressor genes interleukin (IL)-24 and IL-32 in prostate cancer and directly regulates IL-24 in human KB oral cancer cells." (PMID 33109127, 2020). "Moreover, in prostate cancer, miR-205 also upregulated the tumour suppressor genes IL-24 and IL-32 mRNA and protein by targeting their promoters." (PMID 33109127, 2020). "In conclusion, the combination of ionizing radiation and oncolytic adenovirus expressing IL24 could achieve synergistic anti-tumor effect on prostate cancer, and is a promising strategy for prostate cancer therapy." (PMID 32318337, 2020). "In prostate carcinoma cells, miR-205 activates IL-24 and IL-32 by targeting their promoters." (PMID 29471827, 2018). "IL‐24 is regulated by miRNAs such as miR‐205 in oral cancer 11 and prostate cancer." (PMID 28781949, 2017). "Sabutoclax, another BH3-mimetic targeting MCL1, could sensitize prostate cancer cells to IL-24 mediated cytotoxicity." (PMID 25749045, 2015). "Moreover, it was found that ectopic expression of Mcl-1 or Bcl-2 family of proteins in prostate cancer cells led to resistance to mda-7/IL-24-induced cell death." (PMID 25926554, 2015). "Expression of miR-205 was silenced in prostate cancer; since miR-205 transcriptionally activated the expression of tumor suppressors interleukin (IL)-24 and IL-32, miR-205 reintroduction led to the re-expression of IL-24 and IL-32, triggering apoptosis and growth arrest." (PMID 23325049, 2013). "Subsequent studies conducted in prostate cancer cells showed treatment with antioxidants such as N-acetyl-L-cysteine and Tiron or with inhibitors of mitochondrial permeability transition (cyclosporine A and bongkrekic acid) abrogated Ad-IL24-induced apoptosis." (PMID 24377906, 2013). "Also, our study shows that PKA mediates IL-24-induced apoptosis in prostate cancer cell lines." (PMID 40072085, 2025). "Whether IL–24 is involved in the pathogenesis of prostate cancer awaits further investigation." (PMID 26440411, 2015). "In addition, overexpression of Bcl-2 can protect prostate cancer cells from apoptosis induced by MDA-7/IL-24, indicating that the caspase machinery activated by MDA-7/IL-24 in LNCaP cells might be preferentially inhibited only by Bcl-2." (PMID 22629368, 2012).
prostate carcinoma (continued). "Similarly, in prostate cancer cells, adenovirus overexpressing IL‐24 induced apoptosis by producing ceramides (C16, C24, and C24:1); myriocin mediated inhibition of serine palmitoyltransferase was found to inhibit ceramide production and thus block IL‐24 mediated apoptosis." (PMID 40338095, 2025). "We showed for the first time that IL-24 inhibits GSK3β and involves phosphorylation at serine 9 by protein kinase A (PKA) and threonine 390 by p38 MAPK in prostate cancer cells." (PMID 40072085, 2025). "Studies have shown overexpression of IL24 in TRAMP mice, possibly interleukin promotes initial steps of prostate cancer progression by upregulating genes such as matrix metallopeptidase 9, (MMP9) via the JAK-STAT signaling pathway." (PMID 30972102, 2019). "Using the prostate cancer cell line DU-145, which has a complete set of cognate receptors, we demonstrate that MDA-7/IL-24 interacts with these receptors leading to protein and receptor internalization." (PMID 31489119, 2019). "Follow-up studies in prostate cancer and glioma showed JNK activation when IL-24 treatment was combined with radiation." (PMID 24377906, 2013). "Follow-up studies in our laboratory demonstrated IL-24 inhibited VEGF expression in lung and prostate cancer cells through the Src pathway." (PMID 24377906, 2013). "For example, formation of de novo C16- and/or C24-Cer induces apoptosis in lymphoma cells in response to BcR triggering, in prostate carcinoma cells by androgen deprivation and MDA-7/IL-24 stimulation, and in neutrophils by serum depletion." (PMID 23091403, 2012). "Frozen sections of normal and malignant human prostate tissues and human prostate cancer (PCa) cell lines PC-3 and CA-HPV-10, cell lines expressing low and high levels of TGase-4, and recombinant MDA-7/IL-24 (rhMDA-7/IL-24) were used." (PMID 21524313, 2011). "However, the role of TGM4 in the survival of prostate cancer needs to be investigated, particularly considering its opposing effect on MDA-7/IL-24." (PMID 40214422, 2025). "By using adenovirus vector expressing IL-24 (Ad.IL-24), it has been demonstrated that IL-24 binds ER stress markers, BiP/GRP78 and Sigma 1 Receptor (σ1), triggering mitochondrial dysfunction, ROS production, and apoptosis in human prostate cancer cell lines." (PMID 40806452, 2025). "We demonstrated that nonsecreted intracellular IL-24 protein induced apoptosis in prostate cancer cell lines." (PMID 37444474, 2023). "MiR-205 increases the expression of tumor suppressor genes IL24 and IL32 in prostate cancer." (PMID 29471827, 2018). "Concurring with these findings was the report showing IL-24 protein produced in bacteria killed human breast and prostate cancer cells with no toxicity to normal cells." (PMID 24377906, 2013). "Ad-IL24 treatment of prostate cancer cells showed PKR activation in LNCaP cells but not in DU145 cells." (PMID 24377906, 2013). "In prostate cancer cells but not in normal prostate epithelial cells, IL-24 induced autophagy through a canonical signaling pathway involving beclin-1, AuTophaGy-related (ATG)-5 and hVps34." (PMID 24377906, 2013). "We treated several human prostate cancer cell lines (DU145, PC-3, and LNCaP) with IL-24 with or without PKA inhibitor, H-89." (PMID 40072085, 2025).
lung carcinoma (35 papers, 2007 to 2025). "IL-24 Inhibits lung cancer growth by suppressing glioma-associated oncogene homolog 1 (GLI1), associated with marked suppression of the ATM-mediated DNA damage response pathway, which results in increased DNA damage." (PMID 37444474, 2023). "Induction of IL-24, a novel tumor suppressor cytokine in the H1299 lung cancer cell line, was associated with markedly reduced HMGA1 expression level, miR22-3p and -5p levels with a concomitant decrease in pAKT expression." (PMID 35948739, 2022). "As IL-24 is associated with downregulation of lung cancer metastasis, the Hiltonol-mediated increase in IL-24 supports the clinical potential of Hiltonol." (PMID 33562773, 2021). "For example, LINC00152/CYTOR (identified within this class) binds and recruits EZH2 to its target promoters p15 and p21 in gastric cancer and IL24 in lung cancer and thereby causes repression of their expression." (PMID 29757368, 2018). "Another mechanism of IL‐24‐mediated apoptosis documented in lung cancer models stems from upregulation/activation of the double‐stranded RNA‐dependent protein kinase (PKR), which leads to the downstream phosphorylation of eiF2α." (PMID 40338095, 2025). "Recognizing the critical role of SDF‐1/CXCR4 axis, our laboratory conducted studies to examine the impact of IL‐24 overexpression on key target molecules in the SDF‐1/CXCR4 pathway in lung cancer models." (PMID 40338095, 2025). "Preliminary studies in lung cancer revealed that IL‐24 effectively curtailed lung cancer migration and invasion by modulating the expression of PI3K, MAPK and FAK proteins." (PMID 40338095, 2025). "IL-24-expressing oncolytic vaccine virus, against lung cancer, destructed cancer cells through apoptosis and induced a decline in the level of STAT3." (PMID 35752792, 2022). "In this study, BSF modified with low-molecular-weight PEI is used to encapsulate ING4 and IL-24 double gene coexpression plasmids to establish a high-efficiency and low-toxicity gene delivery carrier against lung cancer cells." (PMID 34685354, 2021). "To affirm the physiological significance of PKR, OAS, and IL-24 in lung cancer, we retrospectively examined human primary lung tissues by both TCGA database analyses and IHC (immunohistochemistry) staining." (PMID 33562773, 2021). "Ramesh and colleagues evaluated nanoparticle-mediated delivery of mda-7/IL-24 in primary and disseminated lung cancer." (PMID 35008495, 2021). "The evidence shows that overexpression of IL24 has been found to inhibit the migration of pancreatic cancer, lung cancer, neuroblastoma, and hepatocellular carcinoma cells." (PMID 34955744, 2021). "They observed that IL24-transduced UC-MSCs (IL24-MSCs) inhibited the growth of A549 lung cancer cells by induction of apoptosis and cell cycle arrest." (PMID 32212815, 2020). "Our study provides evidence that IL-24 treatment induces DNA damage, and reduces GLI1 expression and offers an opportunity for testing IL-24-based therapy for inhibiting GLI1 in lung cancer." (PMID 31783569, 2019). "Human umbilical cord-derived MSCs modulated to deliver IL-24 inhibited the exacerbation of lung cancer cells by stimulation of apoptosis and arrest of cell cycle." (PMID 31555593, 2019). "Prior studies have reported IL-24 protein expression is lost in a broad-spectrum of human cancer cell lines and its expression correlated with disease prognosis in melanoma and lung cancer." (PMID 31783569, 2019). "The present study demonstrates the ability of IL-24 to effectively suppress GLI1 in lung cancer cells and induce DNA damage leading to apoptotic cell death." (PMID 31783569, 2019). "Knocking down linc00152 suppressed cell invasion and affects prognosis via interacting with EZH2 and repressing IL24 expression in lung carcinoma." (PMID 29285514, 2017).
lung carcinoma (continued). "Our recent observation of IL-24-mediated AKT inhibition in lung cancer cells and results from another study indicating that the HMGA1/miR-222 axis is involved in AKT regulation prompted this line of investigation." (PMID 27602961, 2016). "Our results demonstrate for the first time that IL-24 inhibits AKT via regulating the HMGA1/miR-222 signaling node in human lung cancer cells and acts as an effective tumor suppressor." (PMID 27602961, 2016). "IL-24-transduced UC-MSCs (IL-24-MSCs) inhibited growth of A549 lung cancer cells by induction of apoptosis and cell cycle arrest." (PMID 25590298, 2015). "A recent study suggests that phosphorylation of MDA-7/IL-24 is required for its anti-cancer activity in a single lung cancer cell line, H1299." (PMID 26460950, 2015). "In a latest study, the effects of IL-24 delivered by mesenchymal stem cells (MSCs) as a therapeutic approach for lung cancer were evaluated." (PMID 25590298, 2015). "In this study, we demonstrated that IL-24-mediated its anti-metastatic activity by disrupting the SDF-1/CXCR4 axis in lung cancer cells." (PMID 25775124, 2015). "The H1299 lung cancer cell line was stably transfected with doxycycline-inducible plasmid expression vector carrying the human IL-24 cDNA and used in the present study to determine the inhibitory effects of IL-24 on SDF-1/CXCR4 axis." (PMID 25775124, 2015). "Demonstration of in vivo efficacy will advance the development of IL-24/CXCR4 based combinatorial therapeutic interventions for lung cancer." (PMID 25775124, 2015). "We previously demonstrated that lung cancer cells expressing exogenous wild-type IL-24 migrate and invade less." (PMID 26009991, 2015). "In continuation with these reports our laboratory has pursued to dissect the PI3K/Akt/mTOR pathway in human lung cancer cells that have been stably transfected to express exogenous IL-24." (PMID 24377906, 2013). "The inhibitory activity of IL-24 on tumor cell metastasis and invasion was first demonstrated by our laboratory using lung cancer as a model." (PMID 24377906, 2013). "Activation of c-Jun NH2-terminal kinase (JNK) by IL-24 and its requirement in IL-24-mediated apoptotic cell killing when combined with radiation was first demonstrated in human A549 lung cancer cells." (PMID 24377906, 2013). "Analysis of IL-24 expression in lung cancer showed an inverse correlation between IL-24 protein expression and disease progression." (PMID 24377906, 2013). "More recent studies conducted in our laboratory has revealed IL-24 when expressed at pharmacological levels in human H1299 lung cancer cells inhibited the Akt/mTOR signaling pathway resulting in suppression of the tumor cell migratory function." (PMID 24377906, 2013). "In vitro studies demonstrated Ad-IL24 markedly reduced the cell invasion and migration ability of human H1299 and A549 lung cancer cells." (PMID 24377906, 2013). "Initial studies conducted in our laboratory showed adenovirus (Ad)-mediated IL-24 gene delivery in human lung cancer cells resulted in induction of tumor cell apoptosis also commonly referred to type-I programmed cell death (PCD)." (PMID 24377906, 2013). "Preliminary results indicate IL-24 effectively inhibits Akt1/2 and its downstream target mTOR in lung cancer cells resulting in inhibition of cell growth, cell migration and invasion." (PMID 24377906, 2013). "The abundance of bacterial populations in the stool of lung cancer patients significantly increased the levels of IL-20, IL-24, CCL-8, and TGF-α in LUAD and LUSC patients, indicating the role of these proteins in bridging the association between gut ecology and lung cancer." (PMID 41376623, 2025). "Therefore, it is conceivable that the anticancer activity of IL-24 suppressed lung cancer cells independently of JAK/STAT." (PMID 33562773, 2021). "The study results show IL-24 as an effective anticancer drug for treating lung cancer." (PMID 31783569, 2019).
lung carcinoma (continued). "Moreover, the efficacy of IL-24 expressing MSCs as a therapeutic cytokine delivery tool for lung cancer was assessed." (PMID 31555593, 2019). "This is a clear indication that IL-24 modulates the ATM-mediated DDR pathway in lung cancer cells." (PMID 31783569, 2019). "In a recent study, we showed that IL-24 inhibited AKT in lung cancer cells." (PMID 27602961, 2016). "On the basis of these data and our observations, we hypothesized that musk may induce the growth repression and the apoptosis of lung cancer cell through up-regulating IL-24 and DDIT3 expressions." (PMID 27931220, 2016). "Finally, our study results provide a basis for the development of an IL-24/HMGA1-based therapeutic approach for lung cancer treatment." (PMID 27602961, 2016). "In the present study, we determined whether (i) IL-24 mediates inhibition of HMGA1 expression in lung cancer cells and (ii) IL-24 mediates AKT inhibition through HMGA1 suppression." (PMID 27602961, 2016). "Thus, a therapy combining IL-24 with HMGA1 siRNA or miR-222-3p inhibitor should present effective treatment of lung cancer." (PMID 27602961, 2016). "To test our hypothesis, in the present study we used a H1299 lung cancer cell line that expressed exogenous human IL-24 when induced with doxycycline (DOX)." (PMID 27602961, 2016). "Musk might induce the growth repression and the apoptosis of lung cancer cells through up-regulating IL-24 and DDIT3 expressions." (PMID 27931220, 2016). "Thus, combining IL-24 with CXCR4 inhibitors is an attractive therapeutic strategy for controlling lung cancer metastasis." (PMID 25775124, 2015). "Since SDF-1 can bind to both CXCR4 and CXCR7, we determined CXCR7 expression in lung cancer cell lines and whether IL-24 inhibited CXCR7 in H1299-IL24 cell line." (PMID 25775124, 2015). "The data thus far indicate: (i) the tumor-suppressor functions of PKR and OAS, which correlate well with the anti-tumor properties of IL-24 in lung cancer and (ii) that expression of PKR and OAS might be regulated by post-transcriptional (or post-translational) modifications." (PMID 33562773, 2021). "For example, cell death occurred in A549 lung cancer cells that were transfected with the ER stress inducing transcript, melanoma differentiation associated gene-7 (mda-7, also known as IL-24), however mda-7 did not affect the survival of non-tumor bronchial epithelial cells." (PMID 32626657, 2020). "Additionally, musk might induce the growth repression and the apoptosis of lung cancer cells through up-regulating IL-24 and DDIT3 expressions." (PMID 27931220, 2016). "For example, the protective role of nuclear factor erythroid 2-related factor 2 (Nrf2) against oxidative stress was inhibited by IL-24 via p38 MAPK and JNK in cervical and lung carcinoma cell lines." (PMID 37444474, 2023). "siRNA-mediated knockdown HMGA1 in combination with IL-24 reduced markedly AKT expression and substantially reduced migration and invasion of cultured lung cancer cells." (PMID 35948739, 2022). "In the present study, we found that IL-24 inhibits GLI1 expression and induces DNA damage in the lung cancer cells." (PMID 31783569, 2019). "Adenovirus-mediated co-expression of ING4 and IL-24 in NSCLC cells resulted in growth suppression and apoptosis in the lung cancer cell lines in vitro." (PMID 31390718, 2019). "In conclusion, our studies demonstrate IL-24 effectively suppresses GLI1 and offers a new IL-24-based treatment approach for targeting GLI1 and achieving improved treatment outcomes for lung cancer." (PMID 31783569, 2019). "Further, the expression levels of IL-24, and HMGA1 proteins were analyzed in cultured human lung cancer cells (H1299, A549, HCC827, H460, and H358) and human normal lung fibroblasts (MRC-9, CCD16, and WI38)." (PMID 27602961, 2016). "Native musk and synthetic musk ketone can up-regulate IL-24 (interleukin family) and DDIT3 (MAPK signalling pathway) in lung cancer cells." (PMID 27931220, 2016).